IL1B (interleukin 1 beta)
Diseases named in the same sentence as IL1B in open-access papers (continued):
Sharing a sentence is not in itself a finding about the gene and the disease.
colitis (continued). "However, it has also been found that the IL-1β and IL-18 produced by NLRP3 inflammatory complexes have protective effects against colitis, although the mechanism is still unclear." (PMID 34462641, 2021). "Accordingly, we observed that the expression levels of genes encoding chemokines (Ccl3, Ccl4, and Ccl6), chemokine receptors (Ccr1, Ccr5, Cxcr2, Cxcl1, Cxcl2, and Cxcl13), and inflammatory factors (Mpo, Il-1β, and Il12) were increased in mice with DSS-induced colitis." (PMID 34795650, 2021). "Moreover, prophylactic EGCG tended to reduce the plasma levels of IL-1β, IL-6, IL-8, and TNF-α in mice with colitis." (PMID 34493333, 2021). "Expression of pro-inflammatory cytokines, including IL-1β, IFN-γ, and TNFα was decreased in colon tissue of EV treated mice compared to DSS-induced colitis mice, whereas expression of the anti-inflammatory cytokines IL-10 and TGFβ were significantly increased in colon tissue of EV treated mice." (PMID 33670708, 2021). "In the colitis patient, TNF-α and IL-1β not only increase the infiltration of neutrophils, but also cause damage to the intestinal barrier, which may induce diarrhea symptoms in patients." (PMID 34199820, 2021). "Upon induction of colitis, significant increases in TNF-α, IL-1β, and IL-6 production were observed in mouse colons, and CME treatment could dose-dependently reduce the production of these cytokines." (PMID 34616300, 2021). "Similarly, the injection of IGNVs loaded with curcumin (IGNVs-Cur), a known anti-inflammatory agent, increased the survival rate of mice with DSS-induced colitis and decreased TNF-α, IL-6, and IL-1β levels in colonic tissue compared with free Cur and GNVs-Cur." (PMID 34065193, 2021). "Inflammatory response plays a key role in the activation of IL-6, IL-1β, and TNF-α in colitis." (PMID 35059326, 2021). "In another study, crocin (100 and 200 ppm~1 and 2% w/v) made a significant decrement in the levels of mRNA expression of TNF-α, IL-1β, IL-6, IFN-γ, NF-κB, COX-2, and iNOS and propagated Nrf2 mRNA expression in the colorectal mucosa following dextran sodium sulfate-induced colitis." (PMID 34956439, 2021). "The present study confirms that HFD augmented the severity of experimental colitis as documented by the increased DAI index, the colonic tissue weight and upregulated colonic expression of proinflammatory biomarkers TNF-α, IL-1β and IL-6 mRNA compared to the mice fed an SD." (PMID 33557311, 2021). "This study showed that L. plantarum ZS62 could regulate IL-1β, IL-12, TNF-α, IL-10, COX-2, iNOS, NF-κB p65, and IκB-α expression in the colon tissues of mice with enteritis to inhibit colitis." (PMID 34745426, 2021). "In DSS colitis, treatment with the FGF15 analogue M52 decreases IL1β, IL6, and TNFα." (PMID 34831429, 2021). "Importantly, the concentrations of CCL-2, IL-1β, and IL-6 were significantly downregulated after DSS-induced colitis mice were treated with curcumin; IL-33 and IL-10 were significantly upregulated." (PMID 34567209, 2021). "Treatment with the NLRP3-dependent procaspase 1, IL-1β, and the IL-18 inhibitor Fclla-2 can reduce colon inflammation in mice, and the NLRP3 inflammasome can initiate and promote the inflammatory response in colitis." (PMID 34408782, 2021). "In this study, consistent with IBD patients, high levels of pro-inflammatory factors (IL-6, IL-1β and TNF-α) were found in mice with DSS-induced colitis, while these pro-inflammatory factors were reduced after treatment with GPH extracts, and high-dose extracts had a stronger inhibitory effect." (PMID 34829046, 2021). "In addition to these effects, RES administration suppressed the expressions of MCP-1, cytokine-induced neutrophil chemoattractant 1 (CINC-1), TNF-α, IL-1β, IL-6 and IL-12 in rats with TNBS-induced colitis." (PMID 32722619, 2020). "DSS-induced colitis did not induce significant change in IL1β and Tnfα expression in colonic cells, compared to the healthy group." (PMID 32156075, 2020).
colitis (continued). "We also observed that, while the pro-inflammatory and pro-fibrotic cytokines IL-1β, MCP-1, and PAI-1 were upregulated in the WT DSS + MC-LR group, knocking out CD40 prevented their upregulation upon MC-LR exposure in the setting of DSS-induced colitis." (PMID 32498446, 2020). "Vagotomy did not affect Escherichia coli-induced colitis, as it did not inhibit Escherichia coli-induced myeloperoxidase activity, IL-1β expression, and NF-κB+/Iba1+ cell counts in the colon." (PMID 32669127, 2020). "Intraperitoneal administration of 5-HT significantly increases the expression of interleukin (IL)-1β and IL-6 and the activity of myeloperoxidase (MPO) by activating 5-HT3 and 5-HT4 receptors in colonic mucosa of colitis mice, while blocking the signal can reduce the pain." (PMID 32117308, 2020). "Similarly, our study showed that SSW suppressed DSS-induced expression of cytokines, such as IL-6, IL-1β, TNF-α, and COX-2, and besides, alleviated DSS-induced colitis symptoms in mice." (PMID 32708415, 2020). "RA treatment significantly decreased the levels of TNF-α, IL-6, and IL-1β in colon tissue in WT mice during DSS-induced colitis, but the effect is not obvious in LXN−/− mice." (PMID 32555320, 2020). "Moreover, tripeptide KPV reduced intestinal inflammation by decreasing IL-1β, IL-6, IL-12, and IFN-γ expressions and attenuated colitis via PepT1." (PMID 32963495, 2020). "We found that the levels of TNF-α, IL-1β, and IL-6 were significantly increased, however, the production of IL-12 was remarkably decreased in LXN−/− mice during DSS-induced colitis, suggesting TNF-α, IL-1β, IL-6 and IL-12 involved in DSS-induced colitis in LXN−/− mice." (PMID 32555320, 2020). "Treatment with L. brevis Bmb6 significantly suppressed the gene expression of TNF-α and IFN-γ, but not IL-1β in DSS-induced colitis mice." (PMID 32630643, 2020). "Cytokines IL-1β, IL-6, and TNF-α can activate NF-κB phosphorylation in colitis." (PMID 33664740, 2020). "Exercise significantly decreased TNBS-colitis macroscopic and microscopic severity, increased colonic blood flow, and attenuated plasma TNFα, IL-6, MCP-1, IL-1β and leptin levels in mice fed either a HFD (70% EAF) or a standard regular chow diet compared to their sedentary counterparts." (PMID 33603741, 2020). "Andrographolide (Compound 10), the bitter diterpene lactone, at 7.5 and 15 mg/kg exerted an anti-colitis and anti-tumor effect by lowering the expression of cleaved CASP1, IL-1β, and mitochondrial membrane potential collapse via the PIK3CA–AKT1–MTOR–RPS6KB1 pathway." (PMID 33101293, 2020). "Likewise, black raspberry extract attenuated TNF-α and IL-1β expressions, and NF-κB and COX-2 activity in mice with DSS-induced colitis." (PMID 32722619, 2020). "Moreover, uvaol significantly reduces mRNA expression and production of pro-inflammatory cytokines (TNF-α, IL-6, IL-1β, and MCP-1) and infiltration of macrophages in colonic tissues of colitis mice." (PMID 32411289, 2020). "Evidences have demonstrated that H. pylori infection decreased the pro-inflammatory cytokines (TNF-α, IFN-γ, IL-1β, IL- 6, IL-17A and IL23) in colitis mouse models, and we also have reported that IL-6 and IL23 expression were down-regulated in H. pylori-infected chronic colitis mice." (PMID 33201893, 2020). "Intraperitoneal injection of these vesicles to mice treated with TNBS decreases the level of the pro-inflammatory cytokines IL-6, IL-1β, IFN-γ and IL-17a and increases the level of the anti-inflammatory cytokine IL-10 in colonic tissue, thus preventing colitis development." (PMID 32365813, 2020). "Likewise, in a mouse model of dextran sulfate sodium (DSS)-induced colitis, upon UC-MSC exosome treatment, macrophage infiltration to the tissue was reduced along with downregulation of IL-1β, IL-6, IL-7, TNFα and iNOS in colon tissue and spleen." (PMID 32595362, 2020).
colitis (continued). "Notably, the plasma levels of IL-6, IL-1β, and TNFα from DSS colitis mice were significantly diminished in mice that received anti-Myl9/12 Ab treatment in comparison to those that received control Ab treatment." (PMID 33584659, 2020). "On day 46 of chronic DSS-induced colitis, there was a residual up-regulation of Il-1β, which was not statistically significant." (PMID 32053891, 2020). "In addition, the alteration of pro- and anti-inflammatory cytokine levels, such as IL-6, IL-1β, TNF-α, and IL-10, in the serum of the DSS-induced colitis mice were determined by ELISA." (PMID 33391246, 2020). "The levels of cleaved (activated) caspase-1 and mature IL-1β were reduced by E. faecalis in the colon tissues of mice with DSS-induced colitis compared to PBS control in wild type mice, but not in NLRP3-deficient mice." (PMID 30823406, 2019). "DSS-colitis model mice produced high levels of the proinflammatory cytokines IL-1β, IL-6 and TNF-α, and B. adolescentis IF1-03 mice produced lower IL-1β, IL-6 and TNF-α, and elevated levels of the anti-inflammatory IL-10, compared to the DSS-colitis model and B. adolescentis IF1-11 protection mice." (PMID 30987344, 2019). "This suggests that, consistent with the pro-inflammatory role of NLRP3 and IL-1β in intestinal inflammation, the E. faecalis pretreatment-induced attenuation of NLRP3 inflammasome activity in macrophages can ameliorate DSS-induced colitis." (PMID 30823406, 2019). "In TNBS-induced colitis, cytokine imbalance was demonstrated by high expression of proinflammatory cytokines (TNF-α, IFN-γ, IL-1β, and IL-17) and low expression of anti-inflammatory cytokines (IL-4 and IL-10) to induce inflammatory damage to the colonic mucosa." (PMID 30894816, 2019). "However, at day 7 exacerbated expression of Il6 and Il1β was observed in the colon correlating to the increase in histological injury in the NikΔIE mice, suggesting that pro-inflammatory mediators are not the early causative mechanism for colitis in NikΔIE mice." (PMID 30737385, 2019). "The data showed that the induction of colitis using TNBS induced an increase in the expression of pro-inflammatory genes such as Tnf-α, Inf-γ, Il-1β, and Il-6 and, on the other hand, a reduction in the expression of anti-inflammatory cytokines such as Il-10 and Tgf-β." (PMID 30717413, 2019). "Next, to confirm the anti-inflammatory effect of SIF on the increased DSS-induced colitis model, we investigated the mRNA expression levels of inflammatory cytokines such as TNF-α, IL-1β, IL-6, MCP1 and inflammatory enzymes iNOS and COX-2 in colon tissues assessed by quantitative RT-PCR." (PMID 31362418, 2019). "Our findings revealed that EEP suppressed protein expression levels of inducible pro-inflammatory enzymes (COX-2 and iNOS) and mRNA expression levels of cytokines (IL-6, IL-1β, and TNF-α) due to inhibitory effects of EEP on phosphorylation of NF-κB and STAT3 in DSS-induced colitis mice." (PMID 30621304, 2019). "It has been previously demonstrated that induction of colitis by 2,4,6-trinitrobenzene sulfonic acid (TNBS) increases cytokine levels (IL-1β and TNF-α) in the hippocampus and that TNF-α is the most important in mediating microglia activation and this was linked to a higher seizure susceptibility." (PMID 31562378, 2019). "Additionally, activation of PXR suppresses the expression of NF-κB target genes including iNOS, IL-1α, IL-1β, IL-6 and TNF-α in the colon of DSS colitis mice." (PMID 31719637, 2019). "This suggests that blocking of the T cell survival signal IL-1β protects B6DC-LMP1/CD40 mice from colitis and identifies IL-1β as colitis-driver, which is present in B6-, but not F1- nor B/c-background." (PMID 30653608, 2019).
colitis (continued). "In C57BL/6 mice, β-sitosterol (20 mg/kg/day) administration for 56 days prevented the colon shortening (~8%) and reduced MPO activity in colon tissue (~35%), what led to a lower level of pro-inflammatory cytokines (IL-1β, TNF-α and IL-6) after colitis induction by high fat diet (60 Kcal% from fat)." (PMID 30987294, 2019). "Importantly our results demonstrated that MCC950 treatment significantly reduced IL-1β, IL-1α, IL17, IL6, IFN-γ, TNF-α and MIP1a in the colitis colon)." (PMID 29872077, 2018). "Nevertheless, the present study showed similar results to a previous study which used a similar colitis model, where IL-17A levels were not influenced by the presence of TNFα and IL-1β." (PMID 30127744, 2018). "Furthermore, LycogenTM ameliorates the inflammation of dextran sodium sulfate (DSS)-induced colitis and cisplatin-induced renal injury by reducing the expression of pro-inflammatory cytokines, TNF-α and IL-1β." (PMID 29642620, 2018). "The western blot results of the in vitro experiments showed that treatment with MCC950 significantly reduced the active caspase-1 p10 and IL-1β in BMDMs and colon explants suggesting that MCC950 inhibits the activation of NLRP3 inflammasome in the colitis model." (PMID 29872077, 2018). "Collectively, data suggests that IL-1β is a partial but not the sole driver of colitis in these mice." (PMID 29725003, 2018). "The pro‐inflammatory cytokines IL1A, IL1B, IL6, and CSF3 and chemokines CXCL1 and CXCL2 were significantly increased, and the frequency of CD11b+Ly6G+ neutrophils was higher in CD11c‐Cre+Rab32f/f colitis mice." (PMID 30338217, 2018). "In addition, mice with DSS-induced colitis exhibit a cytokine profile similar to colitis patients, including overproduction of proinflammatory cytokines TNF-α and IL-1β." (PMID 30166541, 2018). "Moreover, fortunellin (5 or 80 mg/kg) reversed the excessive pro-inflammatory cytokine (TNF-α, IL-1β, and IL-6) profiles and MPO activity in the TNBS-induced colitis model." (PMID 29472916, 2018). "To test whether blocking these pro-inflammatory cytokines can ameliorate colitis in mice, we examined the levels of TNF-α, IL-1β and IL-6 in the inflamed colonic tissue using ELISA." (PMID 29495327, 2018). "In this study, we showed that treatment with SH significantly and dose-dependently decreased the plasma levels of IL-6, IL-1β and TNF-a, suggesting that SH may ameliorate colitis through alleviating inflammation." (PMID 30289941, 2018). "As expected, Fgl2-deficient colonic macrophages isolated from DSS-treated mice produced higher levels of the M1 effector molecule IL-1β, but lower levels of the M2 polarization markers MR, Arg-1, and Fizz1 in DSS colitis than macrophages from DSS-treated WT mice." (PMID 29441068, 2018). "Although genetic deletion of IL-1R did not rule out a contribution from IL-1β downstream of Nlrp1 in DSS-colitis, it did implicate IL-18 in this process." (PMID 30214011, 2018). "In a mouse model of DSS-induced colitis, intraperitoneal administration of ADM was shown to inhibit colon inflammation, and research has shown that administration of ADM reduces the levels of cytokines such as TNF-α, IL-1β, and IL-6." (PMID 28210268, 2017). "This study has generated a successful model of colitis that remains TNFα non-responsive and has demonstrated that IL-1β expression is a major pathway for the progression of colitis in this system." (PMID 28796256, 2017). "When normalized against the sub-optimal or least stable genes, colonic and IL-1β expression levels had a higher variability in DNBS-experimental colitis (DNBS + Ethanol 30%), which shifted the results from a significant up-regulation to a non-significant up-regulation." (PMID 28186172, 2017). "Seven days after colitis induction, the extent of inflammation in the colon was assessed by measuring neutrophil infiltration (MPO activity), proinflammatory cytokine levels (TNF-α and IL-1β), and inflammation parameters." (PMID 29123119, 2017).
colitis (continued). "In particular, treatment with two specific MALT1 inhibitors, MI-2 and mepazine, dose-dependently attenuated the symptoms of colitis in mice through a decrease in protein and mRNA levels of colonic TNF, IL-1β, IL-6, IL-18, IL-17A, and IFN-γ pro-inflammatory cytokines." (PMID 28179906, 2017). "However, in TNBS-induced ileitis and DSS-induced colitis, GLP-2 treatment downregulated expression of inflammatory cytokines, including IFN-γ, TNF-α, and IL-1β, while the anti-inflammatory cytokine IL-10 was increased." (PMID 29270177, 2017). "Moreover, increased expression of inflammatory cytokines, such as IL-1β, TNF-α, and IFN-γ, has been observed in aberrant mucin assembly induced colitis mice." (PMID 29118753, 2017). "In addition, RA resulted in the reduction of the inflammatory-related cytokines, such as IL-6, IL-1β, and IL-22, and protein levels of COX-2 and iNOS in mice with DSS-induced colitis." (PMID 28383063, 2017). "Surprisingly, the results from these studies indicate that IL-18, but not IL-1β, plays a major role in suppressing colitis." (PMID 28955343, 2017). "Serum IL-1β was not increased in TNFα KO Winnie (data not shown), suggesting that systemic secretion of IL-1β was low, perhaps due to the early age and level of colitis." (PMID 28796256, 2017). "Exercise significantly decreased macroscopic and microscopic colitis, substantially increased CBF and attenuated the plasma TNF-α, IL-6, MCP-1, IL-1β and leptin levels while raising the plasma irisin and the plasma and WAT concentrations of adiponectin in HFD mice (p < 0.05)." (PMID 28425943, 2017). "Additionally, the beneficial effects associated with the reduction of inflammatory cytokines such as IL-1β and IFN-γ were further elucidated in a murine model of colitis." (PMID 28194046, 2017). "Colitis rats also had higher MPO activity (indicating neutrophil infiltration into the damaged tissue), higher pro-inflammatory cytokine levels, including TNF-α, IL-1β, and IL-8." (PMID 29176974, 2017). "Cytokine protein arrays showed that the levels of several cytokines, including sICAM-1, IL-1β, IL-16, CXCL10, MCP-1, CXCL9, and TIMP-1, were upregulated (≥50-fold) in the colitis-induced PBS-treated group compared with those in the normal healthy control group." (PMID 28842625, 2017). "In contrast, CD11c+ cells from DC-LMP1/CD40xRag1−/−-mice that do not develop colitis do not express elevated levels of Il23a, Il12a, il1b." (PMID 28276457, 2017). "We found that the levels of active IL-1β and IL-18, which are induced by the inflammasome, but not IL-6 and TNF-α, were associated with increased FLC and inflammatory damage in colitis tissues or tumor formation in AOM/ DSS-induced CAC." (PMID 28701727, 2017). "Either exogenous IL-1β or IL-18 ameliorated the colitis with or without reduction in Th2 cytokine expression, respectively." (PMID 27966619, 2016). "In rats without induction of colitis, intragastric administration of Mutaflor or rifaximin for 7 days failed to affect mucosal concentration of interleukin-1β (IL-1β) or Tumor Necrosis Factor-α (TNF-α) in the colon (resp)." (PMID 27433160, 2016). "In the rats without colitis, administration of obestatin for 7 or 14 days at the dose used was without any effect on mucosal concentration of interleukin-1β (IL-1β) in the colon." (PMID 26798415, 2016). "Consistent with alleviated colitis in REGγ−/− mice, ELISA analysis of colonic explants revealed less production of pro-inflammatory cytokines and chemokines including KC, MIP2α, CXCL5, IL-1β, IL-6 and TNFα in REGγ−/− mice than in WT counterparts." (PMID 26899380, 2016). "We have found that AMT-E exerts intestinal anti-inflammatory activity in the colitis by increasing mucus production, inhibiting neutrophil infiltration, down-regulating TNF-α, IL-1β, and IL-10, as well as suppressing COX-2 and iNOS expression in the mouse colon tissue." (PMID 27527191, 2016).